LEP (leptin)
Diseases named in the same sentence as LEP in open-access papers (continued):
Sharing a sentence is not in itself a finding about the gene and the disease.
breast cancer (continued). "While several adipokines and cytokines are released from the adipose tissue in the mammary gland, breast cancer research has focused predominantly on the effects of leptin and adiponectin, with new research emerging on the role of resistin." (PMID 39525621, 2024). "Taken together, these results indicate that autophagy sustains leptin-induced mitochondrial fitness in breast cancer cells despite their different basal metabolic profiles." (PMID 38228661, 2024). "Treatment of BRCA1 and BRCA2 heterozygous breast cancer cell lines with leptin for 24 h induced significant DNA damage." (PMID 39692821, 2024). "Most in vitro research to date examining the effects of leptin on breast cancer cell migration employed supraphysiological glucose concentrations, and has reported that AMPK is activated by leptin treatment in breast cancer cells." (PMID 39609706, 2024). "For instance, in mouse mammary cancer cell lines treated with leptin, researchers demonstrated an induction of proliferation, attributing it to the crosstalk between Notch-IL-1-Leptin." (PMID 39201370, 2024). "Numerous studies have shown the benefits of combined interventions of exercise plus diet on lipid profile, insulin, adiponectin, leptin and ghrelin in breast cancer patients." (PMID 36839371, 2023). "We assessed changes in leptin levels, adiponectin levels, and the A:L ratio among breast cancer survivors who had a BMI of ≥25 kg/m2." (PMID 37571390, 2023). "As a result, developing a new therapeutic strategy to reduce leptin levels in breast cancer is critical." (PMID 38202341, 2023). "Contrary to the effects of adiponectin, leptin seems to promote the proliferation and development of breast cancer cells." (PMID 36900364, 2023). "Targeting leptin, therefore, appears a rational approach to anti‐MM therapy and in the solid cancer arena this has garnered some interest, although a trial of metformin in breast cancer as a leptin‐reducing metabolic agent was unsuccessful." (PMID 37067783, 2023). "In conclusion, through a comprehensive analysis of 33 publications, we found that LEP gene rs7799039 and ADIPOQ gene rs1501299 were two promising candidate loci in predisposition to breast cancer risk." (PMID 37274250, 2023). "In breast cancer, leptin and leptin receptor (ObR) have been reported to be associated with distant metastasis, worse prognosis, and poor survival." (PMID 36794014, 2023). "The current study presents an innovative approach to alleviate fatigue in breast cancer patients after chemotherapy by regulating the Leptin/AMPK signaling pathway." (PMID 37542585, 2023). "In this study, we aimed to perform a meta-analysis to evaluate the association of genetic alterations in LEP and ADIPOQ genes, as well as their receptor-encoded genes with risk for breast cancer." (PMID 37274250, 2023). "Here the authors show that breast cancer cells derived exosomal miR-204-5p induce leptin signalling pathway in white adipose tissue to promote cancer-associated cachexia." (PMID 37620316, 2023). "Knockdown of leptin in adipose-derived stromal cells co-cultured with ER+ breast cancer cells led to a reduction in tumor growth and expression of metastasis-related genes." (PMID 37800138, 2023). "In this line, it has been shown that high levels of leptin can increase the proliferation of breast-cancer cells and decrease apoptosis in them." (PMID 37238961, 2023). "The concentration of leptin is higher in plasma samples from TME blood than in plasma from peripheral blood samples of obese patients with estrogen receptor-positive breast cancer." (PMID 37686525, 2023). "Taken together, we found, in this meta-analysis, that LEP gene rs7799039 and ADIPOQ gene rs1501299 were two promising candidate loci in predisposition to breast cancer risk." (PMID 37274250, 2023).
breast cancer (continued). "This hormone, leptin, significantly contributes to breast cancer development by enhancing the activation of the signaling pathways associated with cell proliferation while impeding the apoptotic response." (PMID 38202341, 2023). "More than twenty years ago, it was reported that both leptin mRNA and protein levels were increased in several breast cancer cell lines and breast tumors." (PMID 36674935, 2023). "Leptin has been linked to the pathogenesis of cancer by the multitude of mechanisms involving dysregulation of VEGF, JAK/STAT and AKT pathways in breast cancer, pancreatic cancer and thyroid malignancy." (PMID 37378223, 2023). "The overexpression of leptin and its own receptor (ObR) has been found in high-grade breast cancer and is positively correlated with poor prognosis and distant metastasis." (PMID 37509120, 2023). "In this sense, several meta-analyses have confirmed that breast-cancer patients had higher leptin levels." (PMID 37238961, 2023). "Leptin also promotes the proliferation of breast cancer cells by activating the Wnt/β-catenin pathway." (PMID 36755926, 2023). "Leptin supports metastatic progression and tumor recurrence by increasing invasion and migration potential as well as stem-like characteristics in breast cancer cells." (PMID 37571390, 2023). "In a breast cancer model, leptin and IGF-1 have been shown to increase cell proliferation and migration, and to act in synergy in terms of the activation of their receptors, indicating interactions between these two signaling pathways." (PMID 36904077, 2023). "Leptin activates ER-alpha through the MAP-Kinase pathway in breast cancer cells, and in the process, reproduces the features of ER-alpha transactivation." (PMID 36900364, 2023). "In breast malignancy, leptin is secreted by CAFs, and it is responsible for the bidirectional interactions between CAFs and breast cancer cells, leading to the proliferation, migration and invasiveness of breast cancer cells." (PMID 37686525, 2023). "In breast cancer, a leptin antagonist-honokiol, a bioactive polyphenol from Magnolia grandiflora, is reported to activate the liver kinase B1-miR-34a axis and finally inhibit EMT." (PMID 36835413, 2023). "Lastly, we review breast cancer therapies targeting mTOR signaling, leptin signaling, blood sugar reduction, and novel immunotherapy targets." (PMID 37626871, 2023). "To investigate the molecular mechanisms that regulate fatigue after chemotherapy in breast cancer patients, we predicted through the GeneMANIA database that Leptin activates its downstream target gene AMPK." (PMID 37542585, 2023). "Laboratory studies, however, seem to differentiate from epidemiological studies as far as the role of leptin in breast cancer goes." (PMID 36900364, 2023). "They found that IONP-LPrA2 2 reduced leptin-induced cell proliferation in human breast cancer cells through the decreased expression of pSTAT3 and Cyclin D1." (PMID 37509120, 2023). "Secondly, in MDA-MB-231 breast cancer cells, it was shown that cAMP direct elevation reduced leptin-induced cell migration, via both cAMP/PKA- and cAMP-Epac-dependent pathways, and was related to a down-regulation of ITGB3 and FAK proteins level." (PMID 37904233, 2023). "Leptin was also reported to enhance aromatase expression in MCF7 cell lines and consequently promote the synthesis of estrogen and increase the risk for breast cancer." (PMID 36562831, 2023). "The authors describe that, when breast cancer cells were treated with leptin, morphological phenotypical changes occurred that highly resembled fibroblast cells, with increased pseudopodia formation, actin reorganization, and stress fiber formation." (PMID 36900364, 2023). "Leptin induces proliferation and (or) anti-apoptosis effect of breast cancer cells and vascular smooth muscle cells by activating the PI3K pathway." (PMID 37894835, 2023).
breast cancer (continued). "Our rationale for the analyses is based on the predominant fat cell component of the mammary gland, the tissue’s responsivity to insulin and leptin, and its anatomical correspondence to breast cancer." (PMID 37047583, 2023). "This study also revealed the critical role of the Leptin/AMPK signaling pathway in post-chemotherapy fatigue in breast cancer patients through RNA-Seq sequencing data analysis and protein–protein interaction analysis." (PMID 37542585, 2023). "It was demonstrated that CAAs surrounding breast cancer are smaller and exhibit lower lipid content, reduced levels of adipocyte markers (leptin, adiponectin, resistin, FABP4), and overexpression of proinflammatory cytokines and matrix-remodeling proteins." (PMID 37481560, 2023). "Increased serum leptin expression has been reported in breast cancer and pancreatic cancer, whereas lower serum leptin levels have been observed in gastrointestinal cancers like gastric cancer and colon cancer." (PMID 37378223, 2023). "Previous works have also proven a physiological mechanism through which estradiol levels upregulate leptin m-RNA expression in adipose tissue and increase leptin and ObR expression in breast cancer cell lines." (PMID 36900364, 2023). "Experimental data supported that leptin can influence mammary tumor growth and progression through regulation of autocrine/paracrine factors and by modulating the extracellular matrix composition." (PMID 37274250, 2023). "In this study, we investigated the key molecular pathways through which Leptin regulates the AMPK signaling pathway to influence the onset of post-chemotherapy fatigue in breast cancer patients." (PMID 37542585, 2023). "In vitro findings have shown the pro-oncogenic impact of leptin, including cell proliferation, transformation, apoptosis regulation, self-renewal, and reduced sensitivity to breast cancer treatments." (PMID 37509120, 2023). "The results showed that mammospheres (aggregates of mammary epithelial stem cells) were significantly less likely to form in breast cancer cell lines and the patient-derived samples when leptin signaling was inhibited by a full leptin receptor antagonist." (PMID 38202341, 2023). "In particular, leptin-driven Notch and IL-1 signals mediate breast cancer cell proliferation, migration, invasion as well as chemoresistance." (PMID 38152619, 2023). "Previous observations for the effect of exercise on leptin levels in breast cancer survivors were contradictory." (PMID 37571390, 2023). "Above data collectively support the contributory roles of leptin and adiponectin in the pathogenesis of breast cancer." (PMID 37274250, 2023). "Overall, LEP gene rs7799039-G allele and LEPR gene rs1137100-A allele were associated with reduced breast cancer risk relative to the corresponding reference alleles, and the risk was close to statistical significance." (PMID 37274250, 2023). "Aromatase is the rate-limiting enzyme for estrogen synthesis, and leptin can induce aromatase expression through COX-2 expression in breast cancer cells and increase estrogen synthesis, promoting the progression of breast cancer." (PMID 36755926, 2023). "The inhibition of the leptin-mediated signaling pathway correlates with decreased breast cancer cell proliferation and stem cell activity, as well as tumor growth reduction, as reported in the xenograft experiments." (PMID 37509120, 2023). "Clinical evidence showed that women with breast cancer had increased levels of circulating leptin and its receptor." (PMID 37274250, 2023). "In breast cancer cells, leptin and estradiol down-regulate AMPK signaling, but insulin, leptin and estradiol activate the PI3K/AKT signaling cascade, which promotes cancerogenesis." (PMID 37298551, 2023). "Leptin can stimulate the growth and proliferation of breast cancer cells by binding to its receptors on these cells." (PMID 37571390, 2023).
breast cancer (continued). "Leptin was significantly higher in the peripheral blood of breast cancer patients who developed fatigue after chemotherapy." (PMID 37542585, 2023). "Other reported low LEP expression and high expression of Ob-R mRNA in breast cancer tissue correlated with shorter OS and RFS." (PMID 36941557, 2023). "Leptin and ObR are positively correlated, and both are highly expressed in primary and metastatic breast cancer tissue." (PMID 35701840, 2022). "Specifically, the activation of leptin signaling leads to simultaneous activation of multiple oncogenic pathways, leading to increased breast cancer cell proliferation, epithelial–mesenchymal transformation, migration, and invasion." (PMID 35223490, 2022). "Although adipose cells are known to be major source of leptin, it is currently unclear how glutamine metabolism in EC precisely regulates leptin production within the mammary tumor microenvironment." (PMID 36381236, 2022). "Leptin promotes migration and invasion of breast cancer cells by enhancing IL-8 expression in M2 macrophages." (PMID 35701840, 2022). "Five SNPs of LEP and two of LEPR were chosen to evaluate the correlation of selected SNPs with breast cancer susceptibility among women in northern and eastern China." (PMID 35223490, 2022). "Plasma leptin levels are correlated with tumour hTERT levels in human breast cancer (r = 0.484, p < 0.01) and leptin mRNA in human hepatocellular carcinoma is also strongly correlated with hTERT (r = 0.79, p < 0.01)." (PMID 36038791, 2022). "Thereby, adiponectin plays an opposite role compared to leptin in breast cancer progression, but the results greatly depend on their ER status." (PMID 36077676, 2022). "Leptin sustained the resistance of aromatase inhibitor anastrozole in MCF-7 cells, thus leptin disturbance would be beneficial for patients with hormone-resistant breast cancer." (PMID 35701840, 2022). "This study was aimed at investigating the expression of survivin variants S-WT, S-2B, and S-ΔEx3, as well as adipokines LEP and ADIPOQ in breast cancer." (PMID 35342410, 2022). "Several leptin-mediated mechanisms behind this link have been established, including breast cancer invasion, migration, and immune regulation, as well as cancer stem cell enrichment and mesenchymal stem cell dysregulation in the tumor microenvironment." (PMID 35752704, 2022). "Leptin, an adipokine, is involved in the prognosis of breast cancer and promotes EMT via high PKM2 expression and activation of the PI3K/AKT signaling cascade." (PMID 35736645, 2022). "By using GSE65194, we performed ROC curve analysis to access the diagnostic value of four DEmRNAs (TFF1, COL10A1, LEP, and PLIN1) and two DEmRNAs (PGM5-AS1 and TRHDE-AD1) in luminal A breast cancer." (PMID 35692369, 2022). "Adipocyte-secreted leptin also enhanced the HER2 protein levels through a STAT3-mediated up-regulation of Hsp90 in breast cancer cells in vitro." (PMID 35701840, 2022). "Adiponectin was then shown to have the complete opposite effect of leptin on breast cancer and thus, consecutively gained the attention of several research groups." (PMID 36428526, 2022). "Experiments using MMTV-Wnt1 cancer cell lines also revealed the critical of leptin in breast cancer development." (PMID 35563777, 2022). "Leptin also increases receptor expression (VEGFR-2) in ﻿mammary tumours in mice and its transphosphorylation in cellular models (HUVEC)." (PMID 36038791, 2022). "Our results also indicate that the ER signaling pathway in breast cancer cells derived from an obese patient can be sensitized by leptin, an adipokine normally present in patients with increased dysfunctional adipose tissue." (PMID 36591465, 2022). "In support of this notion, ASCs isolated from obese individuals secreted significantly higher levels of leptin that stimulated the proliferation of low and high malignant breast cancer cells." (PMID 36010901, 2022).
breast cancer (continued). "Leptin plays an important role in the connection to the tumor microenvironment specific to breast cancer." (PMID 35989732, 2022). "In breast cancer, the estrogen receptor (ER) is a determinant factor for leptin-mediated autophagy induction." (PMID 36291097, 2022). "Pre-treatment leptin concentrations were higher in E-cadherin positive breast cancers with a tendency to significance (p = 0.0611)." (PMID 36556428, 2022). "Adiponectin was also shown to effectively inhibit leptin-stimulated migration and invasion of breast cancer cells." (PMID 36428526, 2022). "While circulating levels of leptin have a strong direct correlation to the incidence of breast cancer, high levels of adiponectin have a protective effect." (PMID 36591465, 2022). "Leptin is known to have a wide spectrum of biological effects including the sensitization of breast cancer to estradiol-dependent proliferation." (PMID 36591465, 2022). "Insulin stimulates the overexpression of leptin which sets up an autocrine loop to stimulate breast cancer cell growth." (PMID 35406618, 2022). "Combination of 6 protein markers (Adipsin, Leptin, Syndecan-1, Basic fibroblast growth factor, Interleukin 17B and Dickopff-3) resulted in 65% sensitivity and 80% specificity in detecting breast cancer." (PMID 34997107, 2022). "In particular, leptin induces breast cancer stemness and resistance to chemotherapy, through complex mechanisms that comprise signaling cross talk between Notch, IL-1, and leptin (NILCO) and epigenetic downregulation of miR-200c in TNBC cells." (PMID 36077676, 2022). "Then, adipocyte-secreted leptin promoted PAI-1-mediated breast cancer metastasis via activating the STAT3/miR-34a pathway in vivo." (PMID 35701840, 2022). "Leptin plays an important role in the connection of specific microenvironment tumors to breast cancer." (PMID 35989732, 2022). "We recently demonstrated that the adipokine leptin, whose circulating levels correlate with adipose tissue expansion, is an inducer of EV release from breast cancer cells." (PMID 36361728, 2022). "Expression of leptin and its receptor in breast cancer samples correlates with tumor aggressiveness, and leptin/leptin receptor signaling activation is involved in breast cancer progression and metastasis." (PMID 36361728, 2022). "In estrogen receptor (ER)-positive breast cancer cells, leptin increased ATP generation by inducing a metabolic switch to fatty acid metabolism." (PMID 36291097, 2022). "Reducing leptin availability to implanted ER + breast cancer cells (MCF7) significantly decreased the number of metastatic lesions in mice." (PMID 36038791, 2022). "Leptin concentration was negatively correlated with the adiponectin/leptin ratio (rs = −0.787, p < 0.001) as well as the number of years after breast cancer diagnosis (rs = 0.510, p = 0.018), and it was positively correlated with BMI (rs = 0.430, p = 0.050)." (PMID 36232660, 2022). "Based on these results, in the current study, we selected 7 polymorphisms located in the LEP and LEPR genes and identified the association with breast cancer risk in northern and eastern Chinese Han females by conducting a multicenter case–control study." (PMID 35223490, 2022). "The NSE-LEPR-B transgenic mouse has been used to investigate the role of peripheral leptin signaling in breast cancer progression; this transgenic mouse was bred to a MMTV-PyMT mammary tumor mouse model." (PMID 35563777, 2022). "Leptin levels are higher in patients with breast cancer compared to patients who are healthy, particularly in women who are overweight or obese." (PMID 35752704, 2022). "An example is in breast cancer where hyperinsulinemia enhances the growth and invasive potential of breast cancer cells mediated by LEP." (PMID 36362348, 2022).